ABCD3 (ATP binding cassette subfamily D member 3)
Description:
Broad substrate specificity ATP-dependent transporter of the ATP-binding cassette (ABC) family that catalyzes the transport of long-chain fatty acids (LCFA)-CoA, dicarboxylic acids-CoA, long-branched-chain fatty acids-CoA and bile acids from the cytosol to the peroxisome lumen for beta-oxydation. Has fatty acyl-CoA thioesterase and ATPase activities. Probably hydrolyzes fatty acyl-CoAs into free fatty acids prior to their ATP-dependent transport into peroxisomes (By similarity). Thus, play a role in regulation of LCFAs and energy metabolism namely, in the degradation and biosynthesis of fatty acids by beta-oxidation.
Synonyms: PMP70; PXMP1; ZWS2; ABC43; CBAS5; OPDM5
Tractability: Small molecule: a structure with a bound ligand is known. Antibody: UniProt predicts a signal peptide or a membrane-spanning region. PROTAC: UniProt records ubiquitination sites on it; ubiquitination databases record sites on it; its protein half-life has been measured.
Target class: Enzyme; Hydrolase
Gene: Protein-coding gene on chromosome 1 (94,418,242 to 94,518,666, forward strand). Ensembl gene ENSG00000117528.
Subcellular location: Peroxisome membrane
Subcellular location (Human Protein Atlas): Peroxisomes
Pathways (Reactome):
Signal Transduction: RHOA GTPase cycle; RHOC GTPase cycle
Protein localization: Class I peroxisomal membrane protein import
Transport of small molecules: ABC transporters in lipid homeostasis
Gene Ontology:
Molecular function: ATP binding; ATP hydrolysis activity; ATPase-coupled transmembrane transporter activity; fatty acyl-CoA hydrolase activity; long-chain fatty acid transmembrane transporter activity; protein binding; protein homodimerization activity; very long-chain fatty acyl-CoA hydrolase activity; ABC-type transporter activity; identical protein binding
Biological process: fatty acid beta-oxidation; fatty acid biosynthetic process; long-chain fatty acid import into peroxisome; peroxisome organization; very long-chain fatty acid catabolic process; very long-chain fatty acid metabolic process; bile acid and bile salt transport; bile acid biosynthetic process; phytanic acid metabolic process; lipid transport; response to xenobiotic stimulus; transmembrane transport
Cellular component: membrane; peroxisomal matrix; peroxisomal membrane; peroxisome; cytosol; mitochondrion
Genetic constraint (gnomAD): Loss-of-function variants: 27 observed, 77 expected, observed/expected ratio (o/e) 0.35, 90% interval 0.26 to 0.48. The upper end of that interval is the gene's LOEUF score, 0.48, which puts it in group 2 of 6, group 1 being the genes least tolerant of losing a copy. Missense variants: 521 observed, 700.55 expected, observed/expected ratio (o/e) 0.74, 90% interval 0.69 to 0.8. Synonymous variants: 221 observed, 229.73 expected, observed/expected ratio (o/e) 0.96, 90% interval 0.86 to 1.08.
Gene-disease validity (ClinGen):
ClinGen rates the evidence that ABCD3 causes each of these diseases.
congenital bile acid synthesis defect 5 (autosomal recessive): Limited. Any congenital bile acid synthesis defect in which the cause of the disease is a mutation in the ABCD3 gene.
Homologues: Orthologues: chimpanzee ABCD3 (100% identical), macaque ABCD3 (98% identical), dog ABCD3 (97% identical), rabbit ABCD3 (96% identical), mouse Abcd3 (95% identical), rat Abcd3 (95% identical), pig ABCD3 (91% identical), guinea pig ABCD3 (88% identical), tropical clawed frog abcd3 (88% identical), zebrafish abcd3a (83% identical), zebrafish abcd3b (77% identical), Caenorhabditis elegans pmp-2 (59% identical), and 2 more. Paralogues in human: ABCD2 (40% identical), ABCD4 (25% identical).
Diseases named in the same sentence as ABCD3 in open-access papers:
ABCD3 is named in the same sentence as 60 diseases in open-access papers, as found by Europe PMC text mining. Sharing a sentence is not in itself a finding about the gene and the disease. The quoted sentences say what the papers report.
Stroke (10 papers, 2014 to 2023). Sudden impairment of blood flow to a part of the brain due to occlusion or rupture of an artery to the brain. "In our study, within the first week, only 3 out of 233 patients (1.3%) with an ABCD3 − I score ≥ 4 (moderate to high risk) experienced a stroke." (PMID 33708373, 2021). "In a validation cohort of 1,232 patients, ABCD3 and ABCD3-I predicted early stroke at 7, 28, and 90 days but the performance of ABCD3 was similar to ABCD2 in this validation cohort." (PMID 31781015, 2019). "No current studies have examined the relation between ABCD3 and kidney injury, however there has been report of decrease of ABCD3 expression in IR hCMEC/D3 cells in a stroke disease model." (PMID 26655840, 2015). "As for the stroke risk prediction score, ABCD3, but not ABCD2, was significantly associated with seeking medical attention." (PMID 33178128, 2020). "An ABCD2 score ≥2 and an ABCD3 score ≥4 could predict all 12 of these strokes as well as all 25 ipsilateral ischemic strokes that occurred within 14 days." (PMID 25433667, 2014). "There were more patients without recurrent strokes with ABCD3 scores <4 points (17%) than ABCD2 scores <2 points (6%); therefore, it is reasonable to regard the ABCD3 score as clinically more useful for triaging to acute or delayed carotid imaging." (PMID 25433667, 2014).
prostate carcinoma (5 papers, 2011 to 2024). A carcinoma that arises from epithelial cells of the prostate gland. "We are the first to report that ABCD3 is associated with prostate cancer." (PMID 25802834, 2015). "ABCD3 has been shown to be a biogenetic marker for malignancies such as human prostate cancer, ovarian cancer, and non-small cell lung cancer but has hardly been evaluated in glioma." (PMID 35959373, 2022). "Herein we observed immunohistochemical staining of ABCD3 to be localized predominately in the peroxisomal membrane, with some evidence of ABCD3 cytoplasmic pooling during prostate cancer progression." (PMID 25802834, 2015). "We confirmed this finding by monitoring ABCD3 expression in a novel panel of African American and Caucasian prostate cancer paired cell lines." (PMID 25802834, 2015). "These CA patient findings prompted us to independently measure ABCD3 expression in a small number of AA prostate cancer patients." (PMID 25802834, 2015). "In a previously published study, we showed that expression of the ABCD3 gene increased with increasing metastatic potential in a panel of prostate cancer cell lines derived from African American and Caucasian American men." (PMID 25802834, 2015). "In summary, ABCD3 expression correlates with severity of prostate cancer differentiation in the Caucasian prostate cancer patient." (PMID 25802834, 2015). "TMA findings for CA prostate cancer patients in this study prompted us to evaluate ABCD3 expression in the limited number of AA prostate tumors available to us." (PMID 25802834, 2015). "Taken together, these data indicate that increased ABCD3 expression correlates with severity of prostate cancer differentiation in CA patients." (PMID 25802834, 2015). "Verification of ABCD3 in novel AA/CA prostate cancer cell lines revealed an increase in expression with increased metastasis across a novel panel of African American and Caucasian prostate cancer paired cell lines." (PMID 21992608, 2011). "In a separate, small scale study of low and high Gleason African American prostate tumors, ABCD3 expression was elevated and sustained ABCD3 overexpression in primary, low, and high Gleason tissues strongly suggests that prostate cancer is a more aggressive disease in African Americans." (PMID 25802834, 2015). "A similar pattern of expression was observed in the androgen independent metastatic C4-2B cells derived from Caucasian androgen dependent LNCaP cells, thus providing firm evidence of increased ABCD3 gene expression with increased prostate cancer progression in AA tumors." (PMID 21992608, 2011). "Hence, to confirm our results in clinical biospecimen, we monitored expression of ABCD3 in a novel panel of African American and Caucasian prostate cancer paired cell lines." (PMID 21992608, 2011). "Hence, it is rational to speculate that MAPK/ERK pathway via EGFR stimulation may contribute to modulation of ABCD3 gene expression in prostate cancer." (PMID 25802834, 2015). "However there have been no reports to our knowledge of the ABCD3 association with prostate cancer." (PMID 25802834, 2015). "ABCD3 staining was observed predominantly in the peroxisomal membrane of noncancerous and prostate cancer tissues, which was expected because the ABCD3 gene product, PMP70, is a membrane bound peroxisomal protein." (PMID 25802834, 2015). "While the functional role of ABCD3 in prostate cancer is not completely elucidated, this gene warrants further study as a potential biomarker for aggressive prostate." (PMID 25802834, 2015).
X-linked adrenoleukodystrophy (5 papers, 2016 to 2023). X-linked adrenoleukodystrophy (X-ALD) is a peroxisomal disorder resulting in cerebral demyelination, axonal dysfunction in the spinal cord leading to spastic paraplegia, adrenal insufficiency and in some cases testicular insufficiency.
peroxisomal disorders (4 papers, 2015 to 2025). "Recently discovered new peroxisomal disorders such as deficiencies of ABCD3 (PMP70), ACBD5 (see “Mysterious shapers, movers, and regulators of peroxisome dynamics”), and ACOX3 were also addressed elsewhere." (PMID 38244103, 2024). "The only ABCD3-deficient patient was initially diagnosed by the serendipitous finding of absence of ABCD3 staining upon routine immunofluorescence microscopy analysis when screening for peroxisomal disorders in fibroblasts was performed." (PMID 26943801, 2016).
glioma (3 papers, 2021 to 2025). A benign or malignant brain and spinal cord tumor that arises from glial cells (astrocytes, oligodendrocytes, ependymal cells). "We found that ABCD3 expression is associated with tumor grade in glioma patients as ABCD3 is higher in grade IV than in grades II and III." (PMID 35959373, 2022). "According to our results, ABCD3 proves to be an effective diagnostic and prognostic biomarker for gliomas and to have a possible correlation with tumor immune interactions." (PMID 35959373, 2022). "As tumor-infiltrating immune cells (IC) are associated with glioma prognosis, we conducted an analysis to find out if ABCD3 expression was associated with immune infiltration in GBM and LGG." (PMID 35959373, 2022). "To ensure the accuracy of infiltration levels associated with ABCD3, we also assessed how ABCD3 expression correlates with immune infiltration levels in different grades of glioma using TIMER." (PMID 35959373, 2022). "Both the mRNA and protein expression levels of ABCD3 were upregulated in glioma samples and associated with the prognosis and grades of glioma patients." (PMID 35959373, 2022). "Therefore, ABCD3 is likely to be a diagnostic and prognostic biomarker associated with the clinical features and immune infiltration of gliomas." (PMID 35959373, 2022). "In gliomas, high ABCD3 expression was also associated with a poor prognosis." (PMID 35959373, 2022). "In conclusion, we screened an unreported ABCD3 gene by high-throughput bioinformatics analysis of genes significantly altered during treatment of gliomas with the oncolytic viruses EV-A71." (PMID 35959373, 2022). "ABCD3 was among the top 5 downregulated genes in glioma cells after oncolytic virus EV-A71 infection and was significantly enriched in several GO categories." (PMID 35959373, 2022). "ABCD3 expression was found to be an independent prognostic factor of glioma patient prognosis in multivariate analyses." (PMID 35959373, 2022). "Meanwhile, ABCD3 displayed a strong intensity and over 75% quantity in high-grade glioma compared with a moderate intensity and around 50% quantity in low-grade glioma." (PMID 35959373, 2022). "Immunohistochemistry showed positive reactions of ABCD3 protein in cytoplasmic and membranous staining of both high- and low-grade gliomas." (PMID 35959373, 2022). "High ABCD3 gliomas are more likely to occur in tissues with more complex microenvironments, based on this result." (PMID 35959373, 2022). "Our results suggested that ABCD3 could be a potential biomarker for glioma prognosis and immunotherapy response." (PMID 35959373, 2022). "ABCD3 was also closely related to glioma purity and immune score in LGG." (PMID 35959373, 2022). "Our results suggested that ABCD3 could be a potential biomarker for glioma prognosis and immunotherapy response and also further enriched the theoretical and molecular mechanisms of oncolytic virus treatment for malignant gliomas." (PMID 35959373, 2022). "Our studies showed that ABCD3 expression could affect the immune infiltration levels and diverse immune marker sets in glioma." (PMID 35959373, 2022). "Moreover, the Gene Expression Profiling Interactive Analysis (GEPIA) and R package identified the differences and correlations of ABCD3 with glioma." (PMID 35959373, 2022). "We also found that ABCD3 expression could affect the immune infiltration levels and diverse immune marker sets in glioma and, especially, could enhance the malignancy progression phenotype of LGG." (PMID 35959373, 2022). "We also evaluated the influence of ABCD3 on the survival of glioma patients." (PMID 35959373, 2022). "We evaluated the correlations between clinical characteristics and ABCD3 in glioma." (PMID 35959373, 2022).
glioma (continued). "Given that oncolytic virus treatment could trigger an inflammatory immune response in the glioma microenvironment, a systematic analysis of the correlation between ABCD3 and tumor immunity was performed." (PMID 35959373, 2022). "Also, ABCD3 was among the top 5 downregulated genes in glioma cells after oncolytic virus EV-A71 infection." (PMID 35959373, 2022). "Consequently, we conducted the first-ever analysis of ABCD3 expression in large cohorts of human glioma patients, which unveiled the potential role of ABCD3 in glioma." (PMID 35959373, 2022). "Moreover, ABCD3 expression could affect the immune infiltration levels and diverse immune marker sets in glioma." (PMID 35959373, 2022). "Similarly, we found that ABCD3 expression levels in gliomas were related to prognosis." (PMID 35959373, 2022). "In comparison among gliomas with WHO grades, ABCD3 was higher in grade IV than in grades II and III, and there was no statistical difference between grades II and III." (PMID 35959373, 2022). "In the treatment of glioma with EV-A71, we screened a significantly downregulated ATP-binding cassette (ABC) transporter subfamily D member 3 (ABCD3) by high-throughput sequencing data." (PMID 35959373, 2022). "However, ABCD3 did not display a statistically different expression in other glioma subgroups in terms of gender and age." (PMID 35959373, 2022). "However, the expression and correlation of ABCD3 with glioma have not been reported before." (PMID 35959373, 2022).
oculopharyngodistal myopathy (3 papers, 2024 to 2025). Oculopharyngodistal myopathy (OPDM) is a rare, adult-onset hereditary muscle disease. "The expansion of several other CGG repeats located in 5’ UTRs have been implicated in oculopharyngodistal myopathy (OPDM): NOTCH2NLC, GIPC1, LRP12, RILPL1, and ABCD3." (PMID 39868092, 2025).
ovarian carcinoma (3 papers, 2021 to 2022). A malignant neoplasm originating from the surface ovarian epithelium.
prostate tumors (3 papers, 2011 to 2015). "Statistically, the mean expression of ABCD3 was significantly associated with age at ≤ 67 (P = 0.0014), with well-to-moderately and poorly differentiated prostate tumors (P = 0.0009), and with Gleason score of ≤6 (P = 0.0094)." (PMID 25802834, 2015). "This is the first report of ABCD3 expression being statistically significantly associated with Gleason score, age, and severity of differentiation in CA prostate tumors." (PMID 25802834, 2015). "Findings revealed an association of SNPs surrounding ABCD3 gene with basal gene expression of RanGAP1 is important in prostate tumors in AA." (PMID 21992608, 2011). "We found that two SNPs in ABCD3 which strongly interact with the RanGAP1 gene are important in AA prostate tumors." (PMID 25802834, 2015). "In a separate study, we measured ABCD3 expression in African American prostate patients and observed a sustained elevation of ABCD3 in low Gleason score through high Gleason score in AA prostate tumors." (PMID 25802834, 2015). "Herein, we report that increased ABCD3 expression correlates with prostate tumor aggressiveness; specifically increased ABCD3 expression correlates with increasing Gleason score in CA patients." (PMID 25802834, 2015). "Our findings demonstrate that increased ABCD3 expression correlates with Gleason Score in CA prostate tumors." (PMID 25802834, 2015). "This study is a follow-up investigation to determine if ABCD3 can be detected in human prostate tumors." (PMID 25802834, 2015). "However, in AA prostate tumors, ABCD3 expression was higher and was sustained in both low Gleason and high Gleason AA tumors." (PMID 25802834, 2015). "Therefore, we next sought to determine if there is differential expression of ABCD3 in AA prostate tumors." (PMID 25802834, 2015). "Correlation of ABCD3 expression with clinicopathological features showed a positive correlation with patients' age (P = 0.0018), with Gleason score (P = 0.0127), and with well-to-moderately differentiated and poorly differentiated prostate tumors (P = 0.0009)." (PMID 25802834, 2015). "Interestingly, in the African American derived MDA-PCa-2b, we observed significant decreases in ABCD3 and SOS1, which have been previously reported to be associated with African American prostate tumors." (PMID 25004396, 2014). "Moreover, additional studies are needed to define the consequences of ABCD3 overexpression in AA prostate tumors; however due to the intrinsic role of ABCD3 in fatty acid beta oxidation, this would imply that ABCD3 could have a role in enhanced growth in both BPH and malignant cells." (PMID 25802834, 2015).
breast carcinoma (2 papers, 2015 to 2021).